ZACN (zinc activated ion channel)
Description:
Ligand-gated cation channel that allows the movement of sodium and potassium monoatomic cations across cell membranes when activated by zinc (Zn2+), copper (Cu2+), and changes in pH. Could also transport cesium.
Synonyms: L2; LGICZ; LGICZ1; ZAC; ZAC1
Tractability: Small molecule: it belongs to a druggable protein family. Antibody: UniProt places it where antibodies can reach, with high confidence; its Gene Ontology location is reachable by antibodies, with high confidence; UniProt predicts a signal peptide or a membrane-spanning region.
Gene: Protein-coding gene on chromosome 17 (76,071,961 to 76,083,666, forward strand). Ensembl gene ENSG00000186919.
Subcellular location: Cell membrane
Gene Ontology:
Molecular function: ligand-gated monoatomic cation channel activity; ligand-gated monoatomic ion channel activity; pH-gated monoatomic ion channel activity; zinc ion binding; ligand-gated channel activity; extracellular ligand-gated monoatomic ion channel activity; monoatomic ion channel activity; transmembrane signaling receptor activity
Biological process: monoatomic ion transmembrane transport; response to zinc ion; monoatomic cation transmembrane transport; monoatomic ion transport
Cellular component: plasma membrane; transmembrane transporter complex; membrane
Genetic constraint (gnomAD): Loss-of-function variants: 52 observed, 39.88 expected, observed/expected ratio (o/e) 1.3, 90% interval 1.04 to 1.64. The upper end of that interval is the gene's LOEUF score, 1.64, which puts it in group 6 of 6, group 1 being the genes least tolerant of losing a copy. Missense variants: 559 observed, 537.68 expected, observed/expected ratio (o/e) 1.04, 90% interval 0.97 to 1.12. Synonymous variants: 235 observed, 232.4 expected, observed/expected ratio (o/e) 1.01, 90% interval 0.91 to 1.13.
Homologues: Orthologues: chimpanzee ZACN (99% identical), macaque ZACN (89% identical), dog ZACN (75% identical), pig ZACN (71% identical), rabbit ZACN (66% identical). Paralogues in human: HTR3A (21% identical), HTR3C (21% identical), HTR3E (20% identical), HTR3B (18% identical), CHRNA2 (16% identical), CHRNA5 (16% identical), CHRNA7 (16% identical), CHRNB3 (16% identical), CHRNA10 (16% identical), CHRNA3 (16% identical), CHRNA4 (16% identical), CHRNA6 (15% identical), and 33 more.